CEACAM1 (CEA cell adhesion molecule 1)
Description:
[Isoform 1]: Cell adhesion protein that mediates homophilic cell adhesion in a calcium-independent manner (By similarity). Plays a role as coinhibitory receptor in immune response, insulin action and also functions as an activator during angiogenesis. Its coinhibitory receptor function is phosphorylation- and PTPN6 -dependent, which in turn, suppress signal transduction of associated receptors by dephosphorylation of their downstream effectors. Plays a role in immune response, of T cells, natural killer (NK) and neutrophils. Upon TCR/CD3 complex stimulation, inhibits TCR-mediated cytotoxicity by blocking granule exocytosis by mediating homophilic binding to adjacent cells, allowing interaction with and phosphorylation by LCK and interaction with the TCR/CD3 complex which recruits PTPN6 resulting in dephosphorylation of CD247 and ZAP70. Also inhibits T cell proliferation and cytokine production through inhibition of JNK cascade and plays a crucial role in regulating autoimmunity and anti-tumor immunity by inhibiting T cell through its interaction with HAVCR2. Upon natural killer (NK) cells activation, inhibit KLRK1-mediated cytolysis of CEACAM1-bearing tumor cells by trans-homophilic interactions with CEACAM1 on the target cell and lead to cis-interaction between CEACAM1 and KLRK1, allowing PTPN6 recruitment and then VAV1 dephosphorylation. Upon neutrophils activation negatively regulates IL1B production by recruiting PTPN6 to a SYK-TLR4-CEACAM1 complex, that dephosphorylates SYK, reducing the production of reactive oxygen species (ROS) and lysosome disruption, which in turn, reduces the activity of the inflammasome. Down-regulates neutrophil production by acting as a coinhibitory receptor for CSF3R by down-regulating the CSF3R-STAT3 pathway through recruitment of PTPN6 that dephosphorylates CSF3R (By similarity). Also regulates insulin action by promoting INS clearance and regulating lipogenesis in liver through regulating insulin signaling (By similarity). Upon INS stimulation, undergoes phosphorylation by INSR leading to INS clearance by increasing receptor-mediated insulin endocytosis. This inernalization promotes interaction with FASN leading to receptor-mediated insulin degradation and to reduction of FASN activity leading to negative regulation of fatty acid synthesis. INSR-mediated phosphorylation also provokes a down-regulation of cell proliferation through SHC1 interaction resulting in decrease coupling of SHC1 to the MAPK3/ERK1-MAPK1/ERK2 and phosphatidylinositol 3-kinase pathways (By similarity). Functions as activator in angiogenesis by promoting blood vessel remodeling through endothelial cell differentiation and migration and in arteriogenesis by increasing the number of collateral arteries and collateral vessel calibers after ischemia. Also regulates vascular permeability through the VEGFR2 signaling pathway resulting in control of nitric oxide production (By similarity). Down-regulates cell growth in response to EGF through its interaction with SHC1 that mediates interaction with EGFR resulting in decrease coupling of SHC1 to the MAPK3/ERK1-MAPK1/ERK2 pathway (By similarity). Negatively regulates platelet aggregation by decreasing platelet adhesion on type I collagen through the GPVI-FcRgamma complex (By similarity). Inhibits cell migration and cell scattering through interaction with FLNA; interferes with the interaction of FLNA with RALA. Mediates bile acid transport activity in a phosphorylation dependent manner (By similarity). Negatively regulates osteoclastogenesis (By similarity). [Isoform 8]: Cell adhesion protein that mediates homophilic cell adhesion in a calcium-independent manner (By similarity). Promotes populations of T cells regulating IgA production and secretion associated with control of the commensal microbiota and resistance to enteropathogens (By similarity).
Synonyms: CD66a; BGP; BGP1; BGPI
Tractability: Small molecule: a structure with a bound ligand is known. Antibody: UniProt places it where antibodies can reach, with high confidence; its Gene Ontology location is reachable by antibodies, with high confidence; UniProt predicts a signal peptide or a membrane-spanning region. PROTAC: its protein half-life has been measured.
Gene: Protein-coding gene on chromosome 19 (42,507,304 to 42,561,234, reverse strand). Ensembl gene ENSG00000079385.
Subcellular location: Cell membrane (Isoform 1); Lateral cell membrane; Apical cell membrane; Basal cell membrane; Cell junction; Cell junction, adherens junction; Secreted (Isoform 2); Secreted (Isoform 3); Secreted (Isoform 4); Cell membrane (Isoform 5); Cell membrane (Isoform 6); Cell membrane (Isoform 7); Cell membrane (Isoform 8); Cytoplasmic vesicle, secretory vesicle membrane; Cell projection, microvillus membrane
Pathways (Reactome):
Developmental Biology: Regulation of MITF-M dependent genes involved in invasion
Extracellular matrix organization: Fibronectin matrix formation
Hemostasis: Cell surface interactions at the vascular wall
Immune System: Neutrophil degranulation
Gene Ontology:
Molecular function: actin binding; filamin binding; identical protein binding; kinase binding; protein binding; protein phosphatase binding; protein tyrosine kinase binding; bile acid transmembrane transporter activity; calmodulin binding; protein dimerization activity; protein homodimerization activity
Biological process: negative regulation of cytotoxic T cell degranulation; negative regulation of natural killer cell mediated cytotoxicity directed against tumor cell target; negative regulation of T cell mediated cytotoxicity; negative regulation of T cell receptor signaling pathway; regulation of cell migration; wound healing, spreading of cells; angiogenesis; bile acid and bile salt transport; blood vessel development; cell adhesion; cell migration; cell-cell adhesion; cellular response to insulin stimulus; common myeloid progenitor cell proliferation; granulocyte colony-stimulating factor signaling pathway; homophilic cell-cell adhesion; insulin catabolic process; insulin receptor internalization; integrin-mediated signaling pathway; negative regulation of fatty acid biosynthetic process; negative regulation of granulocyte differentiation; negative regulation of hepatocyte proliferation; negative regulation of interleukin-1 production; negative regulation of lipid biosynthetic process; negative regulation of platelet aggregation; and 14 more
Cellular component: anchoring junction; apical plasma membrane; cell junction; cell surface; cell-cell junction; extracellular exosome; extracellular region; membrane; plasma membrane; T cell receptor complex; adherens junction; basal plasma membrane; lateral plasma membrane; specific granule membrane; tertiary granule membrane; microvillus membrane; transport vesicle membrane
Genetic constraint (gnomAD): Loss-of-function variants: 31 observed, 50.68 expected, observed/expected ratio (o/e) 0.61, 90% interval 0.46 to 0.83. The upper end of that interval is the gene's LOEUF score, 0.83, which puts it in group 3 of 6, group 1 being the genes least tolerant of losing a copy. Missense variants: 570 observed, 671.57 expected, observed/expected ratio (o/e) 0.85, 90% interval 0.79 to 0.91. Synonymous variants: 244 observed, 258.25 expected, observed/expected ratio (o/e) 0.94, 90% interval 0.85 to 1.05.
Homologues: Orthologues: chimpanzee CEACAM1 (97% identical). Paralogues in human: CEACAM5 (61% identical), CEACAM6 (54% identical), CEACAM8 (51% identical), PSG8 (35% identical), CEACAM7 (33% identical), PSG7 (33% identical), PSG9 (33% identical), PSG1 (33% identical), PSG6 (33% identical), PSG4 (33% identical), PSG3 (32% identical), CEACAM3 (30% identical), and 12 more.
Diseases named in the same sentence as CEACAM1 in open-access papers:
CEACAM1 is named in the same sentence as 205 diseases in open-access papers, as found by Europe PMC text mining. Sharing a sentence is not in itself a finding about the gene and the disease. The quoted sentences say what the papers report.
melanoma (57 papers, 2006 to 2025). A malignant, usually aggressive tumor composed of atypical, neoplastic melanocytes. "We also reveal evidence for CEACAM1 expression on CD4+ T cells that are phenotypically consistent with FoxP3+ regulatory T cells whose presence correlates with the melanoma-associated TME using multiple approaches." (PMID 38956268, 2024). "A recent study on the important molecule known as CEACAM1, which is linked to increased melanoma cell invasion and migration, found that thin melanomas with higher levels of CEACAM1 overexpression were more invasive." (PMID 36975387, 2023). "For example, it has been observed that a direct interaction between CEACAM-1 expressed on NK cells and CEACAM-1 expressed on melanoma cells was associated with the poor prognosis of melanoma patients." (PMID 38077389, 2023). "CEACAM1, a diagnostic and prognostic marker of melanoma, is found in tumor samples and sera from patients with pancreatic cancer (PC) and is overexpressed in advanced stages of CRC, NSCLC, and other cancers." (PMID 36140182, 2022). "Nevertheless, the detailed function of the four individual CEACAM1 variants in the context of NK-cell mediated antitumor immunity in melanoma is still not fully understood." (PMID 30871206, 2019). "Microarray analysis revealed that CEACAM1 is strongly involved in the melanoma cells’ network of EMT associated genes." (PMID 30089785, 2018). "Here we show in several melanoma cell lines that overexpression or knockdown of SOX9 causes down-regulation or up-regulation of CEACAM1, respectively, in mRNA and protein levels." (PMID 26885752, 2016). "In consequence, recent studies discuss CEACAM1 as a novel diagnostic and therapeutic target in patients of malignant melanoma." (PMID 26539411, 2015). "Here, we show that exclusively the carcinoembryonic antigen-related cell adhesion molecule 1 (CEACAM1) splice variant CEACAM1-4L supports an anchorage-independent signature in malignant melanoma." (PMID 26539411, 2015). "Taken together, we showed that CEACAM1 splice variants act in an antagonistic fashion by modulating phenotypic signatures involved in metastatic dissemination of melanoma cells." (PMID 26539411, 2015). "In this study we demonstrate that serum CEACAM1 (sCEACAM1) levels are correlated with tumor burden in immune-deficient mice xenografted with human melanoma." (PMID 26688824, 2015). "We showed that anti-CEACAM1 renders melanoma cells susceptible to elimination by T cells, both in-vitro and in a human-melanoma xenograft murine model, which maintains antigen-restricted recognition." (PMID 22778766, 2012). "Homophilic CEACAM1 interactions between a MHC-I-deficient melanoma cell line (1106mel) and NK cells significantly inhibited NK killings against cancer cells." (PMID 21731662, 2011). "In fact, clinical studies in a 10-year follow-up indicate that expression of the cell adhesion molecule CEACAM1 in primary tumors in melanoma patients is associated with the subsequent development of metastatic disease." (PMID 16504122, 2006). "Preclinical studies in melanomas show that expression of the cell adhesion molecule, CEACAM1, is an independent factor of the metastasis risk, with a predictive value superior to that of tumor thickness." (PMID 16504122, 2006). "It was shown for melanoma and lung adenocarcinomas, that CEACAM1 upregulation is significantly associated with a poor prognosis." (PMID 16536871, 2006). "The involvement of SOX10 in melanoma immunogenicity has been studied extensively, showing that its loss sensitizes tumor cells to T-cell mediated killing, and it is a direct transcription factor for immune molecules such as CEACAM1 and IRF4." (PMID 39237877, 2024). "In this report, we used a CEACAM1-specific antibody together with mass cytometry to provide global insights into the potential cellular basis for CEACAM1’s immune role in melanoma, its association with the state of treatment, and its expression relative to PD1 and PD-L1." (PMID 38956268, 2024).
melanoma (continued). "However, very few phenotypic details exist concerning CEACAM1 expression on tumor-associated immune cells despite the recognition that its display in many tumors including melanoma is associated with a poor prognosis." (PMID 38956268, 2024). "Moreover, CEACAM1 expression on several tumor entities such as colorectal cancer and malignant melanoma is associated with increased metastatic potential." (PMID 34336716, 2021). "Furthermore, CEACAM1 expression is required for senescence maintenance and detection of high levels of CEACAM1 in melanoma is associated with oxidative stress, immune dysfunction and metastatic disease." (PMID 34066966, 2021). "However, we and others have already showed that CEACAM1 variants differing in their extracellular and intracellular lengths, impact melanoma progression and immune-surveillance in a variant-specific mode of action." (PMID 30871206, 2019). "However, the overexpression of CEACAM-1 is associated with cancers such as thyroid cancer, gastric cancer, and metastasizing malignant melanomas." (PMID 29122006, 2017). "Generating transfectants explicitly expressing just a single splice variant of CEACAM1 in the human melanoma cell line, Ma-Mel-86a we recently identified, that CEACAM1 expression impacts melanoma progression and antitumor immunity in a variant-specific mode of action." (PMID 26539411, 2015). "Loss or lower level of CEACAM1 expression has been detected in colon, prostate, and breast cancers, whereas high expression levels have been found in adenocarcinomas, non-small lung cancers, and melanoma." (PMID 26539411, 2015). "In addition to the widespread CEACAM1 down-regulation, elevated CEACAM1 expression has been observed in lung cancer and malignant melanoma, underlying the importance of studying the mechanisms which determine CEACAM1 expression." (PMID 21050451, 2010). "Moreover, specific CEACAM1 gene mutation inhibits the invasive growth of melanomas, and treatment with anti-CEACAM monoclonal antibodies blocks CEACAM1-enhanced cell invasion and cell migration in a dose-dependent manner." (PMID 16504122, 2006). "Thus, many studies have linked CEACAM1 expression with melanoma progression and metastasis." (PMID 30871206, 2019). "Evasion of NK‐cell‐mediated cytotoxicity in melanoma cells has been proposed to occur through the homophilic binding of CEACAM1 on melanoma cells and NK‐cells." (PMID 41078003, 2025). "The UL16 binding protein 2 and 3 (Ulbp2/3), carcinoembryonic antigen‐related cell adhesion molecule 1 (Ceacam1) and galectin 9 (LgalS9) were identified as possible regulators of melanoma cell resistance to NK‐cell cytotoxicity." (PMID 41078003, 2025). "Since our findings suggested a possible involvement of CEACAM1 in melanoma resistance formation, we examined its role in the IFNγ‐induced melanoma cell transformation." (PMID 41078003, 2025). "We applied a method that allows for the detection of proteins on a single cell to uncover CEACAM1 patterns in melanoma." (PMID 38956268, 2024). "Confocal microscopy confirmed CEACAM1 expression on B cells from metastatic melanoma lesions in conjunction with CD21 that is expressed by memory B cells." (PMID 38956268, 2024). "In the case of B cells, we showed that CEACAM1 is observed on multiple stages of B cell differentiation within the tumors and circulation of melanoma patients." (PMID 38956268, 2024). "We used these to gain a data-driven, high-dimensional CEACAM1 profile in patients with melanoma relative to healthy donor controls." (PMID 38956268, 2024). "Here, we used a highly specific antibody that is predicted to detect all glycoforms and splice variants of human CEACAM1 to provide a comprehensive assessment of human CEACAM1 expression on tumor-infiltrating immune cells through an analysis of melanoma." (PMID 38956268, 2024).
melanoma (continued). "Metacluster C58748 represented CD4+CD45RO+ T cells that expressed CCR6, CCR7, CXCR3 and CXCR5 suggesting TFH cells in melanoma which exhibit elevated CEACAM1 levels in the context of treatment-resistant compared to treatment-naive disease." (PMID 38956268, 2024). "have shown that overexpression of the L-form of CEACAM1 promotes proliferation of 526mel melanoma cells in a SOX2-dependent manner in vitro." (PMID 38077351, 2023). "For example, CEACAM1 was found to promote the invasion and progression of melanoma, pancreatic cancer, non-small-cell lung cancer, etc.." (PMID 36712923, 2023). "CEACAM1 is a biomarker in melanoma, non-small cell lung cancer and pancreatic adenocarcinoma (PDAC), and its increased expression is associated with severe disease." (PMID 36741860, 2023). "Nonetheless, CEACAM1 appeared overexpressed or neo-expressed in thyroid cancer, gastric cancer, and malignant melanoma." (PMID 37691945, 2023). "CEACAM1-3S is associated with enhanced immunogenicity and contributes to improved OS of patients with advanced melanoma; in contrast, CEACAM1-4L promotes tumor progression by downregulating the cell surface expression of the NKG2D ligands MICA and ULBP." (PMID 36438905, 2022). "This has also been questioned by other findings: CEACAM1 is overexpressed in some malignancies including non-small cell lung cancer, melanoma, gastric carcinoma, and metastatic colon cancer." (PMID 34368221, 2021). "SOX9 has been demonstrated to regulate resistance to T-cell-mediated killing in melanoma cells through CEACAM1, a pivotal protein in crosstalk between cancer cells and immune environment." (PMID 34094897, 2021). "CEACAM1 is an intercellular adhesion molecule that regulates cell proliferation, cellular energetics, and inflammation in cancer cells, including melanoma, and has a role in regulating the immune cells in the tumor microenvironment." (PMID 33003483, 2020). "It was reported that SOX9 regulated CEACAM1 (carcinoembryonic antigen cell adhesion molecule 1) expression and immune resistance in melanoma." (PMID 33288737, 2020). "For example, X chromosome linked, sex-determining region Y box 9 (SOX9) transcriptionally regulates CEACAM1 expression in melanoma cells and thereby their immune resistance." (PMID 32226299, 2020). "On the other hand, CEACAM1 appeared overexpressed or neo-expressed in thyroid cancer, gastric cancer, and malignant melanoma." (PMID 30871206, 2019). "CEACAM1 has been described as a tumor suppressor and inhibitor of proliferation in several tumor entities, with the exception of melanoma." (PMID 30871206, 2019). "Data from 3D colony forming assays addressing the individual impact of CEACAM1 isoforms on functional behavior of melanoma cells has identified the CEACAM1-4L version for its potential to drive anchorage-independent growth." (PMID 30871206, 2019). "Analysis of tissue biopsies from melanoma patients that, according to the American Joint Committee on Cancer, spanned stages I to IV, revealed also neo-expression of CEACAM1 in around 80% of biopsies." (PMID 30871206, 2019). "The CEACAM1 based NK cell mediated inhibition of melanoma cell cytolysis was shown to act independently of the MHC class I recognition." (PMID 30871206, 2019). "Expression of CEACAM1-4L on the surface of melanoma cells reduces the expression of MICA, ULBP2, CD155 and CD112 via matrix metalloproteinase (MMP)-mediated shedding of these ligands, resulting in escape of NK cell mediated killing." (PMID 30871206, 2019). "This review focuses on novel mechanistic insights into CEACAM1 isoforms for NK cell-mediated immune escape mechanisms in melanoma, and their clinical relevance in patients suffering from malignant melanoma." (PMID 30871206, 2019). "The prognostic value of CEACAM1 in cancer is controversial: CEACAM1 expression correlates with good prognosis in mammary carcinomas, whereas in melanomas, upregulation of CEACAM1 is accompanied by poor overall survival." (PMID 31847101, 2019).